ENSG00000301109 (novel transcript, antisense to CHD4 and LPAR5)
Gene: Long non-coding RNA gene on chromosome 12 (6,606,515 to 6,627,190, forward strand). Ensembl gene ENSG00000301109.
Gene Ontology:
Biological process: SRP-dependent cotranslational protein targeting to membrane, signal sequence recognition
Cellular component: signal recognition particle, endoplasmic reticulum targeting